APOL1 (apolipoprotein L1)
Diseases named in the same sentence as APOL1 in open-access papers (continued):
Sharing a sentence is not in itself a finding about the gene and the disease.
APOL1 also shares sentences with these, for which no sentence is quoted: end-stage renal disease (28 papers); glomerulopathy (19); clear cell renal cell carcinoma (4); Glomerular sclerosis (3); membranous nephropathy (3); papillary thyroid carcinomas (3); coronary artery disease (2); glomerulonephritis (2); ischaemic stroke (2); metabolic disease (2); nephritis (2); nephrosclerosis (2); prostate carcinoma (2); small cell lung carcinoma (2); Abdominal obesity (1); alopecia areata (1); Alpha-thalassemia (1); Alzheimer disease (1); anemia (1); Anxiety (1); Arthritis (1); atrial fibrillation (1); bacterial pneumonia (1); cardiac arrhythmia (1); cardiomyopathy (1); cervical adenocarcinoma (1); cholera (1); co-infection (1); cognitive decline (1); colon adenocarcinoma (1).
A further 57 diseases each share a sentence with APOL1 in 1 paper.